FGF23 (fibroblast growth factor 23)
Diseases named in the same sentence as FGF23 in open-access papers (continued):
Sharing a sentence is not in itself a finding about the gene and the disease.
iron deficiency (continued). "In fact, serum FGF23 levels are strongly regulated by FGF23 transcription and activity of these enzymes which can be controlled by pro-inflammatory mediators and iron deficiency related to chronic and acute inflammation." (PMID 35216216, 2022). "Our previous work also clearly demonstrated the efficiency of inhibiting FGF23 signaling in stimulating erythropoiesis and rescuing anemia, iron deficiency and inflammation." (PMID 35813388, 2022). "In mice, iron deficiency results in upregulated Fgf23 expression and iFGF23 as well as cFGF23 serum levels, an effect involving hypoxia inducible factor 1 α (HIF1α) which is a transcriptional regulator of FGF23." (PMID 35084563, 2022). "At the same time, iron deficiency and inflammation also affect the expression and fragmentation of FGF23." (PMID 35654784, 2022). "Iron deficiency in these patients was associated with increased iFGF23 levels and in a small open label trial oral iron supplementation substantially lowered FGF23 level in patients with ADHR." (PMID 35629904, 2022). "The delayed onset of ADHR generally manifests in females after puberty, and an iron deficiency has been suggested to drive increases in serum FGF23 levels and manifestation of the disease." (PMID 36246908, 2022). "Iron deficiency has also been shown to increase levels of fibroblast growth factor 23 (FGF23) levels which suppresses 1 α-hydroxylase activity." (PMID 35405984, 2022). "In human CKD cohorts, iron deficiency is associated with increased concentrations of circulating total FGF23, as measured by the C-terminal FGF23 assay." (PMID 35237863, 2022). "The effects of iron deficiency on FGF23 production and metabolism differ in the presence or absence of CKD." (PMID 35461329, 2022). "In contrast, increased transcription of FGF23 due to iron deficiency was previously shown to be attributed to the activation of hypoxia-inducible factor 1 alpha." (PMID 34901334, 2021). "Hepcidin-mediated inflammation-induced iron deficiency in mice stimulates FGF23 transcription and causes increased levels of cleaved FGF23 fragments while intact FGF23 protein remains unchanged." (PMID 34536161, 2021). "This indicates that iron deficiency increases transcription and cleavage of FGF23 simultaneously, and that elevated circulating levels of iFGF23 are only present in situations where FGF23 cleavage is impaired, such as in CKD and ADHR patients." (PMID 33716961, 2021). "In experimental CKD, iron deficiency enhances also intact FGF23 levels, suggesting that besides induction of FGF23 mRNA, iron deficiency only causes high intact FGF23 concentrations when cleavage is impaired as in CKD." (PMID 34536161, 2021). "The mechanism beyond is complex including decreased erythropoietin (EPO) production, iron deficiency, inflammation, and enhanced hepcidin levels, all of which are involved in the regulation of FGF23 transcription and/or post-translational modification." (PMID 34536161, 2021). "Because FGF23 protein in ADHR patients is resistant to cleavage, the intact FGF23 levels were high under conditions of increased transcription of FGF23 stimulated by iron deficiency." (PMID 34901334, 2021). "Fibroblast growth factor 23 (FGF23) has been described as an important regulator of mineral homeostasis, but has lately also been linked to iron deficiency, inflammation, and erythropoiesis." (PMID 33716961, 2021). "We conclude that antenatal oral iron supplementation can redress perturbances in maternal and neonatal FGF23 metabolism induced by maternal iron deficiency during pregnancy." (PMID 33675347, 2021). "Both inflammation and functional iron deficiency stimulate Fgf23 transcription indirectly through the production of erythropoietin (EPO)." (PMID 33716961, 2021). "In CKD patients and kidney transplant recipients, iron deficiency is an important determinant of total FGF23 levels, which has a significant impact on the progression and mortality of CKD." (PMID 34901023, 2021).
iron deficiency (continued). "Taken together, these findings imply that iron absorbed by FC treatment led to reduced FGF23 production and subsequent cleavage, because c-FGF23 is reported to be increased by stimulating an FGF23 production and cleavage under the iron deficiency condition." (PMID 34758731, 2021). "Converging data suggest that the clinical phenotype of ADHR is temporally associated to the existence of iron deficiency, as iron status seems to influence FGF23 concentrations." (PMID 34068220, 2021). "Under conditions of iron deficiency, FGF23 is normally processed in control mice, but its processing is impaired in mice lacking furin in osteoblasts and osteocytes." (PMID 34149625, 2021). "Iron deficiency and inflammation are both able to alter FGF23 transcription via hypoxia inducible factor 1 α (HIF1α)." (PMID 33716961, 2021). "Iron deficiency, erythropoietin treatment or interleukin-1 beta (IL-1β) stimulate FGF23 production by osteocytes and bone marrow hematopoietic cells." (PMID 34149625, 2021). "Iron deficiency results in increased concentrations of hypoxia-inducible factor 1α, which stimulates FGF23 transcription through increased EPO production and perhaps also by directly binding to the FGF23 promoter." (PMID 33675347, 2021). "Analysis of this randomized trial confirms that iron supplementation can reverse elevated FGF23 production caused by iron deficiency in iron-deficient mothers and their neonates." (PMID 33675347, 2021). "In clinical studies, it has been shown that increased inflammation markers correlate with increased serum FGF23 levels, however, the balance between its production and cleavage is maintained, as in iron deficiency." (PMID 33716961, 2021). "Data indicate that inflammation increases FGF23 through an iron-related mechanism and a functional iron deficiency can independently stimulate FGF23 production." (PMID 34055103, 2021). "We showed that unlike what is the case in vitro, furin inactivation in the osteoblastic lineage results only in a modest increase in intact FGF23 under normal or low phosphate diet, but impairs FGF23 cleavage in conditions of iron deficiency." (PMID 34149625, 2021). "FGF23 is a regulator of bone mineral, vitamin D, and iron homeostasis; in turn, FGF23 production is regulated by various factors including iron deficiency and inflammation." (PMID 32935918, 2020). "The proposed effects of iron deficiency and its supplementation are backed by animal data: in rodent experiments, iron deficiency stimulates FGF23 transcription in osteocytes/osteoblasts and in parallel its intracellular degradation to inactive fragments." (PMID 32654663, 2020). "On the other hand, some studies have demonstrated an association between iron deficiency and increase in serum FGF23, and conversely iron transfusion resulted in the decline of FGF23 level." (PMID 33198660, 2020). "Given its interaction with FGF23, correcting iron deficiency should therefore also correct FGF23 excess." (PMID 31834957, 2020). "These discoveries suggest that absolute iron deficiency, characterized by a depletion of both iron stores and circulating iron, promotes FGF23 transcription through Hif1α." (PMID 32982979, 2020). "Both iron deficiency and inflammation increase FGF23 transcription by activating among other signaling pathways, Hif1α, and associated MAPK signaling, in osteocytes." (PMID 32982979, 2020). "One of the specific triggers of FGF23 cleavage by proteolysis appears to be iron deficiency, which contributes to the pathophysiology of anemia in CKD." (PMID 32823844, 2020). "It was shown that iron deficiency can drive FGF23 expression in a mouse model of autosomal dominant hypophosphatemic rickets (ADHR)." (PMID 32982979, 2020). "There are controversies about the effects of iron deficiency or iron overload on the serum level of FGF23." (PMID 33198660, 2020).
iron deficiency (continued). "In mice, ferric citrate administration (5% ferric citrate enriched diet) has led to phosphate binding, correction of iron deficiency, reduced circulating FGF23, and improved CKD outcomes." (PMID 32982966, 2020). "Recent studies have shown that both iron deficiency and iron transfusion exert some effect on the serum FGF23." (PMID 33198660, 2020). "More recently, a prospective study in ADHR patients that co-presented with an iron deficiency phenotype demonstrated that iron repletion in these patients reduced their circulating levels of FGF23 and normalized serum phosphate levels." (PMID 32982979, 2020). "Collectively, these data suggest inflammation and iron deficiency are both potent stimuli of FGF23 production." (PMID 31461904, 2019). "The current findings suggest that FGF23 is important in the pathophysiology of iron-deficiency–and EPO-mediated mortality in the population." (PMID 31170159, 2019). "Iron deficiency directly stimulates bone production and cleavage of FGF23 as well as via enhanced renal erythropoietin production." (PMID 30816126, 2019). "Anemia in CKD is a multifactorial process and with traditional origins, such as impaired erythropoiesis and iron deficiency, studies have devoted considerable attention towards unraveling the contribution of FGF23 to renal anemia." (PMID 31461904, 2019). "Iron deficiency induced by iron chelation stabilized pre-existing HIF1α and increased FGF23 transcription." (PMID 30971944, 2019). "Of interest, the positive association between EPO and FGF23 was in part mediated by functional iron deficiency." (PMID 31170159, 2019). "HIF1α was identified as an intermediate in FGF23 mRNA upregulation: iron deficiency and hypoxia only stabilized pre-existing HIF1α, where inflammation also led to increased cellular expression of HIF1α in bone cell lines." (PMID 30971944, 2019). "A recent study found that both expression and cleavage of FGF23 was promoted by iron deficiency and inflammation, so that secretion of C-terminal fragments was upregulated without significantly affecting serum concentrations of active FGF23." (PMID 30808384, 2019). "Mechanistically, it has recently been shown that iron deficiency stabilizes hypoxia-inducible factor 1-alpha, which in turn up-regulates furin, promoting cleavage of the intact FGF23 (iFGF23) molecule into C-terminal FGF23 fragments." (PMID 31170159, 2019). "Investigation of strategies aimed at correcting iron deficiency and reducing FGF23 levels is warranted." (PMID 31170159, 2019). "Recently, our group and others demonstrated that iron deficiency is a strong determinant of total FGF23 levels in CKD and kidney transplant recipients." (PMID 31170159, 2019). "In healthy women with iron deficiency, the administration of intravenous iron reduced cFGF23, whereas iFGF23 increases transiently, probably due to the reduction of FGF23 cleavage." (PMID 30909513, 2019). "Experimental studies suggest both inflammation and iron deficiency are novel regulators of systemic FGF23 synthesis and secretion." (PMID 31461904, 2019). "Additional studies are required to investigate the disarranged processing events of FGF23 following conditions of acute and chronic inflammation, absolute iron deficiency and elevated EPO levels." (PMID 31461904, 2019). "For example, iron deficiency seems to enhance FGF23 production and also the processing of FGF23 protein." (PMID 29515522, 2018). "Recent studies suggest that inflammation and iron deficiency are involved in this high FGF23 in patients with CKD." (PMID 29515522, 2018). "A recent study using an autosomal dominant hypophosphatemic rickets model demonstrated that iron deficiency stimulated transcription of FGF23 and increased FGF23 cleavage in osteocytes." (PMID 28475601, 2017). "Another study using an animal model of functional iron deficiency due to chronic inflammation confirmed that inflammation and iron deficiency caused an increased FGF23 production and impaired FGF23 cleavage." (PMID 28475601, 2017).
iron deficiency (continued). "Beside its role in phosphate homeostasis, iron deficiency and anemia are associated with increased FGF23 plasma levels." (PMID 29073196, 2017). "A large prospective cohort study that examines the method of iron supplementation is required to clarify the association of FGF23 with the progression of iron deficiency in prevalent HD patients." (PMID 28475601, 2017). "An interesting recent finding is the fact that both inflammatory status and/or iron deficiency can be other potent contributors to the increased FGF23 concentration in patients with CKD." (PMID 27941640, 2016). "As was mentioned previously, there are lines of evidence emerging that suggest a role of inflammation and/or iron deficiency in the increased production of FGF23 in bone." (PMID 27941640, 2016). "Recent findings suggest iron deficiency as a potential mediator of FGF23 expression and murine studies have shown in utero effects of maternal iron deficiency on offspring FGF23 and phosphate metabolism." (PMID 26453792, 2016). "The aim of the current study was to investigate the influence of maternal iron status on circulating FGF23 and mineral homeostasis during early life in rural Gambians; a population in which iron deficiency is common." (PMID 26453792, 2016). "Conversely, the injection of iron polymaltose caused an increase in plasma FGF23 concentration, concomitantly with the decrease of serum phosphate concentration in patients with iron deficiency and preserved kidney function." (PMID 27941640, 2016). "The observation that cFGF-23 decreased significantly after i.v. iron treatment suggests that cFGF-23 reflects the transcriptional activity of the FGF-23 promoter, which is induced by iron deficiency via hypoxia inducible factor 1 alpha (HIF-1α)." (PMID 27907058, 2016). "Recent data demonstrated that iron deficiency can increase cFGF23, possibly as a result of increased FGF23 cleaving." (PMID 26079688, 2015). "This is important because of the known divergence of intact FGF23 and C-terminal FGF23 levels in the setting being studied, namely iron deficiency." (PMID 23902731, 2013). "In a population with iron deficiency, improvement in iron status with iron sulphate was associated with a decrease in plasma C-terminal FGF23 levels." (PMID 23902731, 2013). "We conducted a retrospective analysis of studies carried out from 2006 to 2008 in children from a rural community in The Gambia where iron deficiency anaemia is endemic and where elevated circulating concentrations of FGF23 have been found." (PMID 22465847, 2012). "The study used data from children in a rural Gambian population where dietary calcium intakes are low, rates of iron deficiency and infection are high, and where a wide range of FGF23 concentrations have been reported." (PMID 23098062, 2012). "This suggests that iron deficiency directly stimulates both FGF23 expression and cleavage." (PMID 40142640, 2025). "If FGF23 production and cleavage via post-translational modification are balanced, there is no increase or decrease in net intact FGF23 leading to normophosphatemia, such as in iron deficiency and inflammation." (PMID 41445556, 2025). "Furthermore, the complex interaction between EPO and FGF-23 is discussed, as well as their association with other anemia-related factors and processes such as Klotho, vitamin D, and iron deficiency." (PMID 39684548, 2024). "One of these conditions, iron deficiency, can be corrected to reduce FGF-23 production." (PMID 39684548, 2024). "Interestingly, anemia-related factors, including iron deficiency and erythropoietin, have been shown to increase FGF23 production." (PMID 37752381, 2024). "Specifically, anemia-related factors have been shown to increase FGF23 production, including iron deficiency, which is common in adult and pediatric CKD, and increased erythropoietin, levels of which increase in response to decreasing hemoglobin concentrations in mild–moderate CKD." (PMID 37752381, 2024).
iron deficiency (continued). "Initial observations on patients with autosomal dominant hypophosphatemic rickets (ADHR) suggested that iron deficiency might regulate FGF-23 synthesis." (PMID 39684548, 2024). "It is known that elevated FGF23 concentrations may occur due to iron deficiency and that iron replacement reverses this elevation." (PMID 39045952, 2024). "Thus, iron deficiency not only increases FGF-23 production but also stimulates its cleavage into fragments." (PMID 39684548, 2024). "Factors related to CKD-associated anemia, including iron deficiency, can increase FGF23 production." (PMID 37752381, 2024). "Moreover, high FGF23 levels stimulate hepatic inflammation which, in turn, can stimulate iron deficiency that can feed back to the bone to stimulate FGF23 production." (PMID 39666728, 2024). "Therefore, similar to inflammation and iron deficiency, Epo increases both FGF-23 transcription and FGF-23 cleavage." (PMID 39684548, 2024). "Iron-deficiency-induced increases in FGF23 are accompanied by increased FGF23 cleavage, resulting in marginal to no increase in intact FGF23, with higher total FGF23 and reducing the ability of FGF23 to perform its phosphaturic functions in the kidney and parathyroid." (PMID 39452290, 2024). "Recent evidence has proposed that FGF23 could be involved in the association with indirect markers of inflammation, such as functional iron deficiency (particularly TSAT), anemia with an increased need of EPO, and death." (PMID 38999530, 2024). "Because of the interdependency between dietary phosphorus overload and FGF23, it is challenging to distinguish whether excess FGF23 and/or excess phosphorus directly contribute to anemia and iron deficiency." (PMID 39666728, 2024). "Prior studies have indicated that iron deficiency may alter phosphate metabolism through its effects on fibroblast growth factor 23 (FGF23), a hormone that regulates phosphate homeostasis and is known to be elevated in iron-deficient states." (PMID 39850154, 2024). "Serum iFGF23 levels may be normal in iron deficiency, although higher serum levels of cFGF23 may be observed, as FGF23 synthesis and cleavage are both upregulated in iron-deficient states." (PMID 36836085, 2023). "In addition, iron deficiency regulates vitamin D metabolism potentially through fibroblast growth factor 23 (FGF23), which is secreted by osteocytes." (PMID 37108056, 2023). "Similar alteration of serum FGF23 levels was also found in patients with iron deficiency or IDA." (PMID 37108056, 2023). "However, the early differentiated osteocytes under iron deficiency unexpectedly expressed high amounts of FGF23." (PMID 38040893, 2023). "This reduction in GalnT3 mRNA may contribute to an increase in FGF23 cleavage under conditions characterized by elevated erythropoietin, such as iron deficiency anemia, inflammation, or exogenous treatment with synthetic erythropoietin." (PMID 37681408, 2023). "Concerning the physiological mechanism of the interaction between phosphate and ferritin, iron deficiency may strengthen the association between CKD-MBD and anemia through FGF23, whose level is elevated during iron deficiency." (PMID 37605118, 2023). "Iron deficiency stimulated the transcription of FGF23 in osteocytes and the increase in serum levels of intact, biologically active FGF23 (iFGF23) and C-terminal fragments, a degradation product; biologically inactive FGF23 (cFGF23) in mice has been reported." (PMID 37108056, 2023). "Reducing FGF23 levels in CKD may be accomplished by targeting two key stimuli of FGF23 production—dietary phosphate absorption and iron deficiency." (PMID 35237863, 2022). "A previous study indicated that these CKD complications might be associated with each other, given that iron-deficiency anemia leads to upregulation of fibroblast growth factor-23 (FGF23), a hormone whose primary function is to regulate serum phosphate levels." (PMID 35912897, 2022).